CGAS (cyclic GMP-AMP synthase)
Diseases named in the same sentence as CGAS in open-access papers (continued):
Sharing a sentence is not in itself a finding about the gene and the disease.
diabetes (continued). "Since there is no clearer direct evidence of the link between the cGAS–STING pathway and diabetes, through some indirect literature reports, we can still observe an inextricable link between the cGAS–STING pathway and diabetes and its complications." (PMID 34906241, 2021). "Given the effects of STING agonists in HFD-induced obese mice, it is plausible to hypothesize that DsbA-L may inhibit the cGAS-STING pathway in T cells, potentially suppressing the development and progression of diabetes." (PMID 41020872, 2025). "Conversely, inhibition of the cGAS-STING pathway may have the effect of suppressing JAK–STAT, thus achieving the goal of alleviating the development of chronic inflammation of diabetes." (PMID 38312740, 2024). "There was no clear evidence of a link between diabetes and the cGAS–STING pathway mediated via immune cells until a recent study confirmed a link between DsbA-L and T cells." (PMID 34906241, 2021). "Combined with the performance of agonists of STING in NOD mice, the cGAS–STING pathway may inhibit the onset and progression of diabetes, despite the possible complex regulatory mechanisms." (PMID 34906241, 2021). "At the same time, owing to the contribution of the cGAS–STING pathway in different organs, inhibition of the cGAS–STING pathway-induced inflammatory pathway provides a potential avenue for therapeutic drug development for diabetes and subsequent diabetes-related complications." (PMID 34906241, 2021). "However, whether the cGAS–STING pathway is directly correlated with DsbA-L needs to be further clarified, and whether this inhibition is also present in diabetes still remains to be confirmed." (PMID 34906241, 2021). "Therefore, an investigation of whether the cGAS–STING pathway is participating in and influencing the course of diabetes and its subsequent complications is warranted." (PMID 34906241, 2021). "There is no direct evidence on whether the cGAS–STING pathway affects diabetes." (PMID 34906241, 2021).
Parkinson disease (26 papers, 2020 to 2026). A progressive degenerative disorder of the central nervous system characterized by loss of dopamine producing neurons in the substantia nigra and the presence of Lewy bodies in the substantia nigra and locus coeruleus. "Inflammation is gaining increased recognition for its role in neurodegeneration, and the cGAS/STING pathway is now specifically implicated in conditions such as Parkinson’s disease." (PMID 33031745, 2020). "In Parkinson’s disease (PD), mouse models of α-synucleinopathies, which mimic the neuropathology of PD, show specific activation of cGAS-STING in the nigrostriatal regions, accompanied by elevated cytokine levels and enhanced neuroinflammation." (PMID 41300248, 2025). "Studies on PD have found that when nuclear DNA leaks into the cytoplasm, it can activate the cGAS-STING signaling pathway, triggering an autoimmune response and causing neurological inflammation, worsening Parkinson’s disease." (PMID 39050892, 2024). "In a Parkinson’s disease mouse model, knocking out cGAS/STING signaling rescues the inflammatory phenotype, prevents loss of dopaminergic neurons, and improves motor deficits." (PMID 36248795, 2022). "Given previously reported links between cGAS–STING dysregulation and Parkinson’s disease–associated genes, we tested whether STING controls LRRK2 activity." (PMID 39812709, 2025). "The detrimental effects on Parkinson’s disease may be achieved through the activating of the cGAS-STING protein pathway." (PMID 39050892, 2024). "In addition to AD, Parkinson’s disease (PD) is significantly influenced by cGAS-STING in glial cells." (PMID 39114669, 2024). "Several Parkinson’s disease risk genes, including PINK1, Parkin, and VPS13C, have been linked to the stimulator of interferon genes (STING) signaling pathway that functions as part of an innate immune response downstream of the sensing of cytoplasmic DNA by cyclic GMP-AMP synthase (cGAS)." (PMID 39812709, 2025). "Collectively, these findings demonstrate that the cGAS–STING–YY1 axis promotes astrocyte senescence via upregulation of LCN2 expression, thereby contributing to the progression of Parkinson’s disease." (PMID 41373767, 2025). "Meanwhile, the cGAS-STING pathway participates in neurodegenerative disorders, such as Ataxia-Telangiectasia (A-T), Huntington’s disease (HD), and Parkinson’s disease (PD)." (PMID 38524701, 2023). "Damaged neurons release dsDNA and mtDNA, activating cGAS-STING and exacerbating parkinsonism." (PMID 41153813, 2025).
acute kidney injury (23 papers, 2021 to 2025). Sudden and sustained deterioration of the kidney function characterized by decreased glomerular filtration rate, increased serum creatinine or oliguria. "Cytoplasmic mtDNA released from mitochondria in damaged tubule cells caused inflammation by triggering cGAS-STING signaling pathway in acute kidney injury induced by cisplatin or hypoxia/reoxygenation." (PMID 38972937, 2024). "Previous studies have demonstrated that renal tubular cells mitochondrial damage caused inflammation via activating cGAS-STING signaling in acute kidney injury." (PMID 38972937, 2024). "cGAS-STING pathway activation has been associated with acute kidney injury in humans and can be ameliorated by STING knock-out/inhibition or by cGAS knock-out89 in mouse models of acute kidney injury." (PMID 40603504, 2024). "Additionally, mitochondrial DNA damage causes inflammation by activation of cGAS-STING signaling in acute kidney injury." (PMID 38848144, 2024). "This suggests that the activation of the cGAS-STING pathway plays an important role in acute kidney injury." (PMID 39114669, 2024). "SFP/NGN NFs effectively attenuated cisplatin-induced acute kidney injury by facilitating mitochondrial autophagy, decreasing the release of mtDNA and inhibiting the cGAS-STING pathway." (PMID 39737190, 2024). "After acute kidney injury, we recently reported that Mitofilin depletion results in the activation of the cGAS/STING/p-p65 pathway that favors the transcription of inflammatory cytokines in the nucleus." (PMID 37107296, 2023). "In pathological renal failure, the decreased mtDNA quality may contribute to the activation of the cGAS-STING pathway and its downstream inflammatory response." (PMID 40427438, 2025). "Finally, targeting cGAS may be an attractive strategy for attenuating uremia-induced acute kidney injury." (PMID 37189826, 2023). "In cases of acute kidney injury (AKI), a nephrotoxic reagent induced mtDNA leakage into the cytosol and activated cGAS-STING signaling, ultimately resulting in renal tubular inflammation." (PMID 38036728, 2023). "In a model of cisplatin-induced acute kidney injury, cisplatin caused mtDNA leakage into the cytoplasm through the mitochondrial outer membrane BAX/BAK pore, activated the cGAS-STING signaling pathway, and resulted in inflammation and acute kidney injury." (PMID 37667279, 2023). "Our previous study also demonstrated how β-HB supplementation ameliorates cisplatin-induced acute kidney injury (AKI) by inhibiting NLRP3 inflammasome activation and the cGAS-STING pathway." (PMID 36235648, 2022). "Studies have shown that YSXZF can inhibit the cGAS/STING pathway, reduce the expression of inflammatory factors such as TNF-α, IL-3, and IL-1β, and decrease IRF1 activity, which in turn reduces the inflammatory response and prevents acute kidney injury." (PMID 39737190, 2024). "Mitochondrial damage and release of mtDNA into the cytosol activated cGAS-STING dependent IL-6 production without type I interferon in a model of cisplatin-induced acute kidney injury." (PMID 35967325, 2022). "Instead, consistent with a model of cisplatin-induced acute kidney injury, we observed no type I interferon production, and increased mitochondrial dysfunction following treatment with A23187-EVs, suggesting that in response to A23187-EVs, macrophage mtDNA may activate the cGAS-STING signaling axis." (PMID 35967325, 2022).
Stroke (23 papers, 2020 to 2025). Sudden impairment of blood flow to a part of the brain due to occlusion or rupture of an artery to the brain. "Mechanistically, post-stroke cytosolic DNA accumulation activates cGAS, triggering the STING-dependent production of type I interferons (IFNs) and pro-inflammatory cytokines that drive microglial polarization toward a neurotoxic (M1) phenotype." (PMID 41471264, 2025). "These divergent findings highlight the cGAS/STING/IRF3 pathway’s pivotal role in post-stroke immune regulation, orchestrating immune cell activation, cytokine dynamics, neuroinflammation, apoptosis, and tissue repair during stroke recovery." (PMID 41471264, 2025). "The protective mechanism of neuroprotective factors after stroke has also been reported to be related to the cGAS‐STING pathway." (PMID 38459658, 2024). "A substantial body of research has documented that in preclinical stroke models, the activation of cGAS‐STING signaling pathway exacerbates brain damage." (PMID 38459658, 2024). "Liao and colleagues were able to show that the cytosolic cGAS pathway was upregulated in microglia after experimental stroke." (PMID 37212886, 2023). "Our work developed a new nano-drug that balances the cGAS-STING axis to enhance the therapeutic impact of stroke by combining the DNase-memetic Ce4+ enzyme and STING inhibitor synergistically." (PMID 37502677, 2023). "For instance, stroke activates the cyclic GMP-AMP synthase (cGAS) pathway, which induces inflammation and brain damage." (PMID 37045990, 2023). "Consistently, cell-specific genetic ablation of cGAS in microglia protected against brain damage, improved neurobehavioral performance, and reduced cell death after stroke to a similar extent as compared to the pharmacological inhibition of cGAS through A-151." (PMID 37550658, 2023). "Given that our study constructed a novel nano-drug combining DNase-memetic Ce4+ enzyme and STING inhibitor for balancing the cGAS-STING axis to improve the therapeutic effect of stroke." (PMID 37502677, 2023). "After stroke, tPA therapy greatly enhanced the expression of cGAS and the activation of STING in the microglia; it also increased the production of the downstream signals of pTBK1, pIRF3, and IFN-β within the ischemic cortex." (PMID 36618820, 2022). "We study the inflammatory cascade on dsDNA recognition and investigate the neuroprotective effect of cyclic GMP‐AMP (cGAMP) synthase (cGAS) antagonist A151 and its mechanisms of neuroprotection in a mouse model of experimental stroke." (PMID 32239625, 2020). "The improved stroke recovery upon A-151 treatment was further accompanied by reversal of cGAS/STING-mediated upregulation of AIM2 inflammasome- and pyroptosis-associated molecules, neutrophil infiltration as well as the production of pro-inflammatory factors and pyroptosis in microglia." (PMID 37550658, 2023). "Finally, Shi and colleagues used CXCR4-coated versatile nanoparticles carrying A151, a cGAS inhibitor, modulating inflammation after stroke." (PMID 37212886, 2023). "Even though the exact molecular process of cGAS in nerve inflammation after stroke remains unclear and requires more investigation, the cGAS–STING pathway surely participates in the response to CNS injury." (PMID 36195926, 2022). "Similarly, we also observed that the transcription level of cGAS increased in the ischemic penumbra from the brain of the Rhesus monkey stroke model." (PMID 32863951, 2020). "Here, downregulation of cGAS in microglia mitigated OGD/R- and I/R-induced neuroinflammation and attenuated I/R-induced brain injury, which strongly suggests that cGAS could be a potential drug target for the treatment of stroke." (PMID 32863951, 2020). "Using these mice, the specific importance of cGAS in stroke could be characterized." (PMID 37915571, 2023).
Stroke (continued). "Further, the activation of the cGAS-STING pathway could promote the formation of a pro-inflammatory microenvironment and the cGAS-STING expression in microglia was upregulated after stroke, and conditional knockout of cGAS in microglia attenuates ischemic/reperfusion-induced brain injury." (PMID 36994418, 2023). "A151 treatment resulted in reduced expression of cGAS, AIM2, IL-1β and IL-18 after experimental stroke and decreased infarct volume and improved neurological deficits after stroke." (PMID 37212886, 2023). "In parallel with the heightened deposition of dsDNA during ischemia, we identified abundant expression of cGAS and STING in the ipsilateral hemisphere compared with the contralateral hemisphere on day 3 following stroke." (PMID 32239625, 2020). "Despite not serving as a ligand for cGAS, HMGB1 facilitates the formation of U-turns in DNA, thereby promoting cGAS-mediated innate immunity, which may prove crucial in the context of the pronounced HMGB1-induced injury observed following stroke." (PMID 37915571, 2023). "Additionally, the authors discovered that the activation of the cGAS–STING pathway and its mediated type I IFN response affected the NET-mediated impact on tPA-related cerebrovascular complications in stroke." (PMID 36618820, 2022).
triple-negative breast carcinoma (23 papers, 2020 to 2025). An invasive breast carcinoma which is negative for expression of estrogen receptor (ER), progesterone receptor (PR), and human epidermal growth factor receptor 2 (HER2). "Pantelidou and colleagues showed that in a cGAS-proficient model of triple-negative breast cancer, silencing of STING abrogates CXCL-10 upregulation following olaparib treatment." (PMID 39851178, 2025). "The paclitaxel-induced MN formation led to the cGAS-STING pathway activation was previously demonstrated in triple-negative breast cancer." (PMID 40786100, 2025). "For instance, in triple-negative breast cancer cells, when there is an error in chromosome segregation, the cGAS-STING signaling pathway is activated." (PMID 40567603, 2025). "pTBK1, pSTAT1 expression and cGAS-STING pathway scores are all increased in triple-negative breast cancers compared to other subtypes." (PMID 38167507, 2024). "Eribulin, a microtubule-targeting agent, promotes cGAS-STING signalling expression in triple-negative breast cancer cells by facilitating the cytoplasmic accumulation of mtDNA, IFN-β production, and downstream interferon-stimulated genes." (PMID 37448962, 2023). "For example, in triple-negative breast cancer, lung adenocarcinoma, and non-small cell lung cancer, activation of cGAS-STING promotes distant or brain metastases and leads to poor patient outcomes." (PMID 37670034, 2023). "ERI enhances nuclear localization of cGAS, resulting in hyper-activation of the cGAS-STING pathway in triple-negative breast cancer cells." (PMID 38106033, 2023). "Namely, recent elegant studies on triple-negative breast cancer lines and animal models have shown that chromosomal instability in neoplastic cells may trigger the cGAS-STING pathway via the formation of micronuclear vesicles." (PMID 37120444, 2023). "However, the DDR-induced cGAS-STING-mediated IL-6 -signal transducer and activator of transcription 3 pathway in triple-negative breast cancer has been associated with reduced patient survival." (PMID 37448962, 2023). "For instance, exosomes bearing CSF-1 from triple-negative breast cancer cells can induce monocyte differentiation towards proinflammatory macrophages with IFN response, partly through the cGAS/STING signaling pathway, and are associated with better clinical outcomes." (PMID 37670933, 2023). "Knockdown-cGAS accelerates proliferation of triple negative breast cancer cells." (PMID 38106033, 2023). "Based on previous reports of the cGAS/STING pathway being highly expressed and coupled to immune cell infiltration in triple-negative breast cancer with replication stress, we explored the expression of cyclin E1, cyclin D1 and c-Myc and immune infiltration." (PMID 39751944, 2025). "We report here that MUC1-C is necessary for intrinsic expression of the RIG-I, MDA5 and cGAS cytosolic nucleotide pattern recognition receptors (PRRs) and the cGAS-stimulator of IFN genes (STING) in triple-negative breast cancer (TNBC) cells." (PMID 35681561, 2022). "Triple-negative breast cancer (TNBC) cells release EVs that promote the differentiation of monocytes into various macrophage subsets, thereby boosting the pro-inflammatory interferon response via cGAS/STING." (PMID 40443670, 2025). "Concomitant inhibition of the cGAS-STING axis and growth factor signaling mediated by the epidermal growth factor receptor (EGFR) synergistically suppressed the development of tumor organoids derived from primary tumor tissues of triple-negative breast cancer (TNBC)." (PMID 35992877, 2022).